NLRP3 (NLR family pyrin domain containing 3)
Diseases named in the same sentence as NLRP3 in open-access papers (continued):
Sharing a sentence is not in itself a finding about the gene and the disease.
depression (continued). "Therefore, our data provide evidence for a mechanism through which depression aggravates immune‐mediated hepatitis, which involves hepatic NLRP3 inflammasome overactivation induced by depression‐associated intestinal dysbiosis." (PMID 41503678, 2026). "Hence, it is important to elucidate the impact of depression‐associated gut dysbiosis on the activation of the NLRP3 inflammasome during the progression of immune‐mediated hepatitis." (PMID 41503678, 2026). "In addition, NLRP3 mediates the activation of inflammasomes, leading to depression-like behaviors caused by estrogen deficiency and hippocampal inflammation in mice." (PMID 40936908, 2025). "In summary, the NLRP3 inflammasome and its associated inflammatory signaling pathways play significant roles in both the pathogenesis and potential therapeutic intervention of depression." (PMID 40936908, 2025). "Abnormal activation of the NLRP3 inflammasome is associated with the occurrence of depression." (PMID 40699781, 2025). "Aberrant NLRP3 activation has been linked to mitochondrial dysfunction, and the NLRP3 inflammasome serves as a critical mediator between immune dysregulation and the development of depression." (PMID 40001487, 2025). "Moreover, it has been found that the PI3K/AKT signaling pathway and NLRP3 inflammasome are linked in the pathogenesis of depression, and the activation of the former stimulates the expression of downstream nuclear factor-κB (NF-κB)." (PMID 41179813, 2025). "Additionally, the activation of the NLRP3 inflammasome has been implicated in the progression of depression in mice models." (PMID 40002529, 2025). "The NLRP3 inflammasome is critically implicated in the pathophysiology of depression." (PMID 41194915, 2025). "In depression, deficiency of Kir6.1 activates the NLRP3 inflammasome through excessive accumulation of mitochondrial ROS, triggering caspase-1-dependent cleavage of gasdermin D (GSDMD), leading to astrocyte pyroptosis and the release of the pro-inflammatory cytokine IL-1β." (PMID 40936908, 2025). "Interestingly, activation of the NLRP3 inflammasome has been linked to the beginning and progression of CNS disorders such as anxiety and major depression." (PMID 38941031, 2025). "The activation of NLRP3 inflammasome promotes the secretion of Caspase-1, which secretes downstream cytokines, NF-κB, TNFα, and other pro-inflammatory cytokines, and then induces apoptosis, which NLRP3 cascade has been implicated CNS disorders such as depression." (PMID 40308754, 2025). "Additionally, the NF-kB pathway is implicated in the activation of microglial NLRP3 inflammasome and A1-like astrocytes in the depression model." (PMID 38659577, 2024). "By rectifying gut microbiota microenvironment dysbiosis, FMT reinstates a balanced microbial ecosystem, influencing key targets such as the Sig-1R and NLRP3 inflammasome, which are implicated in neuroinflammatory and neurochemical pathways associated with depressive disorders." (PMID 38983862, 2024). "We propose that NLRP3 may be an important marker in the association between depression and MI, but this difference may become statistically significant in a larger sample and with more severe depression." (PMID 37763063, 2023). "Currently, studies indicated that NLRP3 inflammasome may be a bridge between stress and stable intestinal environment, suggesting that the effects of microbiota on depression may be associated with the NLRP3 inflammasome." (PMID 37293210, 2023). "The NLRP3 inflammasome has been linked to the pathophysiology of depression and may offer a fresh approach to treating the condition." (PMID 36909194, 2023). "The purpose of the present study was to investigate mechanisms underlying H2S prevention of depression-like behavior and to examine whether NLRP3 inflammasome and mitochondrial function contribute to it." (PMID 37626978, 2023).
depression (continued). "At the same time, the activation of NLRP3 inflammasome promoted the disorder of Aβ metabolism and the high phosphorylation of tau protein, which might also be an important reason for depression as a risk factor for AD." (PMID 37165444, 2023). "The NLRP3 inflammasome processes pro-IL-1β into mature interleukins and act as a pro-inflammatory mediator, it has been confirmed that IL-1β was elevated in the serum of depression patients and associated with depression inventory scores." (PMID 36859349, 2023). "This pathological change in the gut microbiota composition may even strengthen the stress/depression phenotype and increase the risk of other NLRP3-related co-morbid disorders." (PMID 35546876, 2022). "The NLRP3 inflammasome is closely associated with depression and neuroinflammation." (PMID 35498131, 2022). "To verify whether EA treatment modulates this molecular signaling mechanism, we detected and quantified the TLR-4/NF-κB and MAPK and NLRP3 inflammasomes, which is a risk factor of depression." (PMID 35087621, 2022). "Previous studies implicated that the NLRP3 inflammasome in the development of depression." (PMID 35496273, 2022). "Interestingly, NLRP3 inflammasomes have recently been suggested to link psychological stress, depression, and systemic illness and have been linked to severe mental illness." (PMID 35082268, 2022). "Our findings suggest that NLRP3 DNA methylation may predispose to depression-related brain structural changes by increasing NLRP3 inflammasome-related neuroinflammatory processes in MDD." (PMID 35628578, 2022). "Furthermore, recent research has shown that Nrf2 regulates NLRP3 activation in LPS-induced depression, and the Nrf2/NLRP3 pathway is closely linked to the development of depression." (PMID 35634375, 2022). "In addition, several studies have revealed the association between depression and NLRP3 inflammasome activation." (PMID 34559953, 2021). "Three types of PRRs have been identified, namely, Toll-like receptors (TLRs), NOD-like receptors (NLRs), and C-type lectin receptors (CLRs); of these, TLR4 and the inflammasome-associated NOD-like receptor pyrin domain containing 3 (NLRP3) are most closely linked to depression." (PMID 33505499, 2021). "This work illustrates that targeting the NLRP3/Casp-1/GSDMD–mediated pyroptosis may provide potential therapeutic benefits to stress-related astrocyte loss in the pathogenesis of depression." (PMID 34877938, 2021). "Recent findings provide new insights into the pathogenesis of depression and anxiety mediated by intestinal flora, suggesting that the effects of gut microbiota may be associated with the NLRP3 inflammasome." (PMID 33935710, 2021). "Moreover, fluoxetine represses NLRP3 inflammasome stimulation in macrophages as well as the hippocampus in mice models of long-term mild-stress, implying an encouraging therapeutic scenario for therapy of NLRP3 inflammasome-associated depression." (PMID 34443594, 2021). "Given the astrocytic loss in depression and the correlation between pyroptosis and nervous system diseases, it is tempting to speculate that the NLRP3/Casp-1/GSDMD–dependent pyroptotic process contributes to the astrocytic loss in the context of depression." (PMID 34877938, 2021). "The changes were associated with active NLRP3 levels in the prefrontal cortex and depression‐ and anxiety‐like behaviors, indicating that increased blood BHB levels may represent stress vulnerability." (PMID 33609086, 2021). "In addition, increases in the NLRP3 inflammasome and caspase-1 levels are associated with increases in serum IL-1B and IL-18 levels in patients with major depression." (PMID 34422020, 2021). "The mechanism of depression caused by psychological stress may be to increase the sensitivity of innate immune cells, such as microglia and monocytes, to activate NLRP3 inflammasomes, which further promote the release of proinflammatory cytokines." (PMID 32166013, 2020).
depression (continued). "Furthermore, the NLRP3 inflammasome inhibitor MCC950 ameliorates cognitive disorders as well as anxiety- and depression-like behaviors in db/db mice, which is associated with the inhibition of hippocampal NLRP3 inflammasome activation." (PMID 29495433, 2018). "A better understanding of the multifaceted mechanisms of the actions of these atypical drugs on NLRP3 inflammasome signaling can be postulated to contribute to improvements in the efficiency of the pharmacotherapy of depression, particularly in that associated with microglia immunoactivation." (PMID 29976873, 2018). "Furthermore, NLRP3 has been associated with LPS-induced depression in a murine model, suggesting a role of inflammasomes and Nod-like receptor signalling pathways in the immunity–depression relationship." (PMID 26631274, 2016). "Moreover, inflammatory factors linked to the NLRP3 inflammasome could serve as potential biomarkers for the early diagnosis and monitoring of treatment for depression-CVD comorbidity." (PMID 41194915, 2025). "Building upon this foundation, further exploration of the upstream molecular mechanisms regulating their release (such as the activation of the NLRP3 inflammasome pathway) may provide crucial insights into the multifaceted molecular processes underlying neuroimmune dysregulation in depression." (PMID 40936908, 2025). "Through interactions with inflammatory pathways, the NLRP3 inflammasome not only facilitates the progression of depression but may also aggravate the pathological processes associated with CVD, thereby creating a vicious cycle that intensifies disease symptoms." (PMID 41194915, 2025). "NLRP3 inflammasome not only is involved in the progression of CAD by aggravating the inflammatory response of myocardial cells but also participates in the occurrence of depression by multiple pathways, especially for the pyroptosis caused by neuroinflammation." (PMID 39012662, 2024). "However, it is intriguing to hypothesize that NLRP3 could potentially serve as a candidate for risk assessment for both depression and AMI." (PMID 37763063, 2023). "Therefore, the NLRP3 system may be a key mediator of the association between depression and neuroinflammation." (PMID 35498131, 2022). "Recent evidence suggests that the causative agent of depression may be associated with NLRP3." (PMID 36339940, 2022). "Additionally, numerous pieces of evidence suggest a significant association between the NLRP3 inflammasome activation in the stress responses and depression's underlying causes, and inhibition of it exerts as a promoting therapeutic target for depressive disorders." (PMID 35634375, 2022). "In summary, the release of inflammatory cytokines mediated by TLR4/NLRP3 inflammasome signaling pathway-induced immunoinflammation may represent a common pathogenic mechanism underlying the development of gastrointestinal diseases and depression." (PMID 33505499, 2021). "The release of inflammatory cytokines mediated by TLR4/NLRP3 inflammasome signaling-induced immunoinflammatory activation may represent a common pathogenic process underlying the development of gastrointestinal diseases and depression." (PMID 33505499, 2021). "The NLRP3 inflammasome is a multiprotein complex that initiates inflammatory cytokine production upon activation, plays a critical role in the development of major depression." (PMID 41556446, 2026). "Depression aggravates immune‐mediated hepatitis through disruption of intestinal barrier integrity and overactivation of hepatic NLRP3 inflammasome." (PMID 41503678, 2026). "Our previous study reveals that the NLRP3 inflammasome‐mediated neuroinflammation is involved in the development of depression, in which the adaptor protein ASC acts as a critical linker within the inflammasome complex." (PMID 41556446, 2026). "Several studies have indicated that the NLRP3 inflammasome is involved in the progression of depression." (PMID 41503678, 2026).
depression (continued). "Collectively, these findings demonstrate that NLRP3 activation is involved in the progression of both depression and immune‐mediated hepatitis." (PMID 41503678, 2026). "L. formosensis, isolated from the livers of mice colonized with microbiota from patients with depression, played pivotal roles in the disruption of intestinal epithelial integrity and overactivation of NLRP3 in the liver." (PMID 41503678, 2026). "NLRP3 activation is elevated in peripheral blood mononuclear cells of patients with depression and can be reversed by antidepressant therapy." (PMID 41503678, 2026). "Mechanistically, we revealed that the detrimental effects of depression were mediated by intestinal barrier dysfunction and NLRP3 overactivation." (PMID 41503678, 2026). "Across various animal models of depression, the NLRP3 inflammasome has been demonstrated to play a crucial role in the disease's pathophysiology." (PMID 41194915, 2025). "The inhibitor MCC950 reduced NLRP3, IL-1β, and IL-18 levels in the hippocampus and improved depression behavior." (PMID 41048915, 2025). "To explore the mechanisms and therapeutic potential of the NLRP3 inflammasome in the comorbidity of depression and CVD, we systematically reviewed recent literature." (PMID 41194915, 2025). "The NLRP3 inflammasome is regarded as a principal mediator in the development of depression, given its widespread expression in neurons, microglia, and astrocytes." (PMID 41194915, 2025). "Many compounds, such as fluoxetine, MCC950 and berberine, block depression by inhibiting the NLRP3 inflammasome." (PMID 40075143, 2025). "Alterations in the intestinal microbiota can activate the NLRP3 inflammasome pathway, triggering inflammatory responses within the CNS and contributing to the pathogenesis of depression." (PMID 41179813, 2025). "The NLRP3 inflammasome is also involved in the onset and progression of other CNS diseases, such as depression, autoimmune encephalitis, and epilepsy." (PMID 40075143, 2025). "Fecal microbiota transplantation (FMT) from healthy mice to postpartum MDD (PPD) mice alleviated depression/anxiety-like behaviors, reduced NLRP3/caspase-1-mediated inflammation in the gut and hippocampus, increased SCFA levels." (PMID 41048915, 2025). "The results indicate that NLRP3 inflammasome is persistently activated in patients with both depression and CVD, and this activation correlates with disease severity." (PMID 41194915, 2025). "More broadly, under stress- and depression-related paradigms, EE reprogramed microglia toward anti-inflammatory phenotypes and restrained NF-κB signaling, reducing NLRP3 priming." (PMID 41357236, 2025). "Overall, this study reveals a novel antidepressant mechanism of FMN in terms of neuroinflammation regulated by microglia polarization and NLRP3, and also provides a potential therapeutic target for depression treatment." (PMID 40275171, 2025). "Nonetheless, the decline in estrogen levels postmenopause increases women's susceptibility to NLRP3-mediated inflammation, consequently raising the incidence of both CVD and depression." (PMID 41194915, 2025). "Stress-induced depression triggers the activation of the NLRP3 inflammasome in the hippocampus to increase the expression of IL-1β." (PMID 40075143, 2025). "In summary, PF mitigates LPS-induced depression through NLRP3 suppression and Nrf2/HO-1 activation, offering a promising therapeutic strategy for inflammation-related depression-like behavior in mice." (PMID 40427467, 2025). "Activation of the NLRP3 inflammasome induces metabolite dysregulation and functional changes in intestinal flora, which exacerbate neuroinflammation and depression-like behaviors through the “gut-brain axis”." (PMID 41179813, 2025). "In conclusion, the NLRP3 inflammasome represents a critical molecular mechanism linking depression and CVD, as well as a potential target for combined therapeutic strategies." (PMID 41194915, 2025).
depression (continued). "Salvianolic acid B, the metabolite of Salviae miltiorrhizae, abolished chronic mild stress-induced depression through suppressing oxidative stress and neuro-inflammation via regulating NLRP3 inflammasome activation." (PMID 40612748, 2025). "inhibit NLRP3 activation in rat hippocampus and prefrontal cortex tissues to alleviate depression-like symptoms." (PMID 40529498, 2025). "Our results suggested that PF improved the LPS-induced depression-like behavior in mouse models of depression, inhibiting Keap1-mediated Nrf2 degradation and activation of the NLRP3 inflammasome." (PMID 40427467, 2025). "In HFD-induced depression models, the expression of NLRP3, ASC, caspase-1, and IL-1β is markedly elevated." (PMID 41194915, 2025). "In NLRP3-deficient mice, gut microbiota regulates astrocyte dysfunction through circular RNA HIPK2, thereby ameliorating depression-like behavior." (PMID 40936908, 2025). "Depression models induced by other methods in mice also exhibit neuroinflammation related to the NLRP3 inflammasome in the hippocampus, suggesting that the serum NLRP3 inflammasome can be used to detect and assess the severity of depression." (PMID 40075143, 2025). "Currently, various strategies to treat depression by targeting the NLRP3 inflammasome have emerged, including NLRP3 pathway inhibitors, natural compounds, other therapeutic agents, and nonpharmacological approaches." (PMID 41194915, 2025). "The emergence of depression is closely related to the stimulation of mature NLRP3 inflammasome triggering the activation of Caspase-1, which in turn promotes the maturation and release of pro-inflammatory cytokines." (PMID 40308754, 2025). "In the present study, BDNF/TrkB/PI3K/AKT was used as the core pathway, combining its upstream and downstream substrates and NLRP3 inflammasome pathway together to explore the therapeutic mechanism of Sini San in depression." (PMID 41179813, 2025). "Recent studies have shown that activation of the NLRP3 inflammasome complex plays a role in the mediation of depression." (PMID 40573262, 2025). "As a therapeutic target, the activation of the NLRP3 inflammasome is central to the shared pathology of depression and CVD." (PMID 41194915, 2025). "This study investigates the role of geniposide in upregulating lncRNA Six3os1 to inhibit the MAPK/NLRP3 signaling axis and regulate astrocyte pyroptosis in a mouse model of depression, addressing a gap in the current literature." (PMID 41341504, 2025). "The activation of the NLRP3 inflammasome has been observed in several animal models of depression, such as LPS, stress, and ovariectomy induction models." (PMID 40497971, 2025). "In this study, we noted marked microglial activation in the hippocampal CA3 region of depressed mice, resulting in pro-inflammatory cytokine production and NLRP3 inflammasome activation, which worsened depression." (PMID 40427467, 2025). "For instance, animal models based on LPS-induced NLRP3 inflammasome overactivation are increasingly used, revealing that some antidepressants mitigate the depression-related phenotype via NLRP3 modulation." (PMID 39005130, 2025). "Melatonin alleviates oxidative stress and pyroptosis, improves LPS-induced depressive-like behavior, and provides a novel therapeutic approach for depression by inhibiting the activation of the NLRP3 inflammasome in microglia." (PMID 40552323, 2025). "Acupuncture exerts its antidepressant effects by regulating the NLRP3 inflammasome in the prefrontal cortex of rats with chronic stress-induced depression." (PMID 41194915, 2025). "Among the various types of inflammasomes, the NLRP3 inflammasome has been the most extensively studied, with its abnormal activation closely associated with the pathogenesis of CVD and depression." (PMID 41194915, 2025).